APOE (apolipoprotein E)
Diseases named in the same sentence as APOE in open-access papers (continued):
Sharing a sentence is not in itself a finding about the gene and the disease.
tumor (continued). "Interestingly, apolipoprotein E (ApoE) is a Trem2 ligand and both Trem2 and ApoE are expressed by a subpopulation of tumour-associated macrophages." (PMID 34794433, 2021). "In GC, ApoE has recently been identified as a potential tumor-associated marker." (PMID 29567987, 2018). "Additionally, the overexpression of APOE has also been associated with tumor progression and poor survival, which could play a role in cancers that develop in the peritoneal cavity or metastasize to the adipose-rich omentum." (PMID 39339686, 2024). "Besides, APOE+TREM2+ macrophages were considered as tumor associated macrophages which were enriched in tumors from patients who recurred following surgery, suggesting the potential immune modulating function of APOE." (PMID 37380987, 2023). "In addition, functional ApoE exosomes delivered from tumor-associated macrophages (TAMs) to cancer cells could induce the activation of the PI3K/Akt signaling pathway, increasing the metastasis of GC cells." (PMID 35066729, 2023). "Consequently, apoE is associated with tumor grades and properties by the mediator LXR." (PMID 32306242, 2020). "This significant increase of cytotoxic cell number indicated that the inhibitory effect of ApoE KO on tumor growth and metastasis may be associated with increase of infiltration of CD8α+ T cells and CD57+ NK cells in urethane-induced lung tumor tissues and lung metastasis tissues." (PMID 31275318, 2019). "The percentage of APOE in the tumor core (8.5 ± 4.1%) and tumor edge (8.2 ± 4.3%) was significantly higher than that in the peritumoral normal tissue (3.6 ± 1.5%) in the ALTS1C1 model." (PMID 40745073, 2026). "The results showed that the majority of APOE spots were found within GFAP + astrocytes at the tumor edge in the ALTS1C1 model (72.5 ± 10.7%)." (PMID 40745073, 2026). "This study provides the first evidence that astrocytes at the tumor edge are activated and upregulated for APOE secretion." (PMID 40745073, 2026). "Flow cytometry analysis of the cell composition in the ALTS1C1 tumor was performed to further identify the source of APOE in the tumor core." (PMID 40745073, 2026). "Together, these studies suggest the versatile role of APOE in tumor progression, including lipid metabolism, immune regulation, and tumor cell intrinsic effects." (PMID 40745073, 2026). "A similar increase in activated astrocyte and APOE expressing activated astrocyte at the tumor edge was also found in the GL261 model." (PMID 40745073, 2026). "Our IF staining results showed a higher amount of cholesterol and APOE at the tumor edge than at the tumor core." (PMID 40745073, 2026). "The APOE expressing activated astrocyte was increased at the tumor edge (21.8 ± 10.2%) and significantly increased at the tumor core (33.0 ± 10.2%) compared to the peritumoral normal tissue (15.7 ± 3.7%)." (PMID 40745073, 2026). "It was found that APOE accumulated at the GBM tumor tissue margin, with levels higher than in adjacent tissues, both in the mouse GBM model and in patient tissue chips." (PMID 40745073, 2026). "An increased number of APOE mRNA spots (APOE spots) at the tumor edge, compared with the contralateral brain, was observed." (PMID 40745073, 2026). "ex., typical tumor drivers BCAN, APOE, and EGFR or genes associated to neuronal function like EGR1, FOS, and MARCKS)." (PMID 40188875, 2026). "Specifically, the effects of APOE+ macrophages on ccRCC tumor progression, their contribution to reshaping the immune microenvironment, and their impact on immunotherapy and underlying mechanisms are not yet fully elucidated." (PMID 40303328, 2025).
tumor (continued). "By employing the "AUCell" package, a comparative analysis of androgen responsiveness was conducted on tumor cells from both the control and APOE-overexpressing groups." (PMID 40365288, 2025). "These two findings are of great interest given that APOE+ macrophages have been reported to exist and play an immunosuppressive role in the primary tumor mass of various types of cancer." (PMID 40835684, 2025). "In short, we identified an exclusive tumor cell subpopulation MP3 in D‐TGCT and confirmed the role of these tumor cells in regulating differentiation of CD34+ Fbs toward APOE+ Fbs and MMP3+ Fbs through COL6A3 − (ITGAV + ITGB8) interaction." (PMID 40126353, 2025). "Recent studies have also highlighted the critical role of APOE+ macrophages in tumor immune evasion and poor responses to ICIs." (PMID 40356222, 2025). "Building on our previous findings regarding the spatial arrangement of immune cell populations, we next focused on the localization and functional role of APOE+ macrophages at the tumor border." (PMID 40303328, 2025). "While APOE is primarily known for its role in lipid metabolism, recent studies have highlighted its involvement in cell proliferation, tumour angiogenesis and metastasis." (PMID 39810624, 2025). "To elucidate the biological characteristics of APOE-high PCa, we established subcutaneous tumor models for both control and APOE-overexpressing groups." (PMID 40365288, 2025). "Through a combination of in vitro and in vivo experiments, we discovered that ApoE predominantly modulates the function of immune cells within the tumour microenvironment." (PMID 40662483, 2025). "The tumour growth of APOE‐expressing cells was substantially slower compared to the control group, while these genetic modifications did not affect mouse body weight." (PMID 39810624, 2025). "Through single‐cell transcriptomic sequencing, this study provides a high‐resolution landscape of the LUAD tumour microenvironment and identifies a distinct subpopulation of APOE+ macrophages characterised by unique transcriptional features." (PMID 40736341, 2025). "After the addition of the anti-APOE antibody, the clonal formation ability of the tumor cells was significantly reduced (all P < 0.05)." (PMID 40303328, 2025). "Flow cytometry analysis further revealed that in these ApoE‐knockout tumour‐bearing mice, both the circulating and intra‐tumoural levels of myeloid‐derived suppressor cells (MDSCs) were elevated." (PMID 40662483, 2025). "The same study reported that MCF-7 cells expressing ApoA-I and ApoE and implanted into athymic nude mice significantly promoted tumor growth." (PMID 40149482, 2025). "We show that HAVCR2 + ADAM + myeloid cells have increased transcription of TREM2 and APOE, which have been proposed as pro-tumor macrophage markers." (PMID 39953623, 2025). "Previous studies have primarily concentrated on the role of APOE in specific immune cells and its impact on the tumor microenvironment, specifically in relation to myeloid-derived suppressor cells (MDSCs) and macrophages 16,21,22." (PMID 40365288, 2025). "Overexpression of APOE in tumour cell lines reversed their proliferative phenotype in both cell and animal experiments." (PMID 39810624, 2025). "The presence of stroma‐derived ApoE plays a crucial part in anti‐tumour immunity by carefully modulating the populations of myeloid immune cell." (PMID 40662483, 2025). "These integrative results further emphasise the extensive involvement of APOE+ macrophages in modulating the complexity of the tumour immune microenvironment." (PMID 40736341, 2025). "Many studies have highlighted how APOE influences immune cell behavior and tumor-immune interactions, suggesting that it plays a critical role in modulating the immune microenvironment." (PMID 39990672, 2025).
tumor (continued). "In our study, we demonstrated that TMZ stimulates tumor cells to secrete APOE, which then interacts with increased SCARB1 to initiate a series of cascade reactions." (PMID 41390817, 2025). "Overall, TMZ induces the autocrine of APOE by tumor cells, leading to dysregulation of lipid metabolism and activation of the Wnt pathway, and subsequent DNA damage repair." (PMID 41390817, 2025). "This enabled the detection of RAW 264.7 macrophages within tumor and atherosclerotic plaque sites in tumor-bearing and ApoE -/- mouse models." (PMID 41011618, 2025). "Our research has revealed that the downregulation of OVOL1 results in diminished APOE expression both in mRNA and protein levels, which consequently decreases cholesterol uptake by the tumour cells." (PMID 40437660, 2025). "Meanwhile, the putative immune correlations (e.g., APOE with macrophages) should be interpreted cautiously, as bulk RNA-seq lacks resolution to disentangle tumor-intrinsic vs. microenvironmental contributions." (PMID 41343534, 2025). "utilized the fat‐mass and obesity‐associated protein (FTO) to epigenetically inhibit APOE expression in PTC, leading to the inhibition of glycolytic metabolism via the IL‐T/JAK/STAT3 signalling pathway and subsequent suppression of tumour growth." (PMID 39810624, 2025). "Our observations revealed that APOE+ macrophages and cytotoxic T lymphocytes (CTLs) exhibited enhanced interactions with all three tumor subtypes, thereby highlighting the significant spatial interplay between immune and tumor cell subtypes." (PMID 40470730, 2025). "APOE overexpression significantly reduced tumor cell proliferation and invasion, both in vitro and in vivo, by activating the ABCA1‐LXR axis." (PMID 39810624, 2025). "Strikingly, APOE− tumour cells exhibited minimal interaction with NK, B and T cells in both primary tumour tissues and lymph nodes, while APOE+ tumour cells strongly interacted with these cell types." (PMID 39810624, 2025). "We found that macrophages exposed to CM from SMS low-expressing tumor cells were less polarized toward Macro_APOE, and the M2 marker genes expression and the proportion CD206+ macrophages also declined." (PMID 40963562, 2025). "L + M cells exhibit high expression of APOE, a molecule with multifaceted roles in the tumor microenvironment, including lipid metabolism, cell signaling, and immune modulation." (PMID 40678806, 2025). "We identified differentially expressed genes (DEGs) between APOE+ and APOE− tumour cells in both thyroid and lymph node samples." (PMID 39810624, 2025). "It was also discovered that TAMs suppress adaptive immune responses via the Dectin-1/Galectin-9 axis and promote the production of immunosuppressive factors, such as CXCL1 and CXCL5, in tumor cells through the upregulated expression of apolipoprotein E (ApoE)." (PMID 40723238, 2025). "One study found that FTO works by inhibiting growth and glycolysis, likely by reducing the expression of APOE which acts to promote tumor growth via the IL-6/JAK2/STAT3 pathway." (PMID 40243425, 2025). "Tumor-derived APOE, which is a critical lipoprotein, appears to play a key role in this process, which explains the increase in cellular lipid uptake." (PMID 41390817, 2025). "The increased secretion of APOE induced by tumor chemotherapy results in brain cell aging, the establishment of a proinflammatory milieu, and disturbances in normal brain communication." (PMID 41390817, 2025). "To further explore the role of the CD99‐driven network in the interaction between APOE‐positive and APOE‐negative tumour cells and immune cells, we focused on these cell types at both the primary thyroid site and lymph node metastasis site." (PMID 39810624, 2025).
tumor (continued). "A pan-cancer analysis has emphasized the pivotal role of APOE+ macrophages in influencing anti-tumor immunotherapeutic outcomes." (PMID 40303328, 2025). "Our results demonstrated that APOE overexpression was accompanied by increased ABCA1 expression in tumour tissues." (PMID 39810624, 2025). "To further investigate the biological functions of APOE in pNENs, we first examined the high expression of APOE in tumor tissues compared to normal tissues by using immunohistochemistry." (PMID 39990672, 2025). "Previous studies have shown that APOE can promote the proliferation and migration of tumor cells, inhibit the tumor immune microenvironment, and be related to resistance to immunotherapy." (PMID 40963562, 2025). "Our cell line experiments and nude mouse tumorigenicity assays further indicated that APOE overexpression inhibited tumour cell proliferation and migration." (PMID 39810624, 2025). "From an initial set of 76 patients diagnosed with PTC, we utilized qRT-PCR to assess the expression levels of four characteristic genes associated with OSPTCC subtypes (APOE, APOC1, DEPTOR, and SQSTM1) in patient tumor samples." (PMID 40650680, 2025). "We further investigated the interaction between APOE+/APOE− tumour cells with immune cells in lymph nodes." (PMID 39810624, 2025). "BLT-1 currently resides in early-phase clinical development with demonstrated preclinical efficacy in disrupting APOE/SCARB1-mediated tumor progression pathways." (PMID 41390817, 2025). "In this context, tumor-derived apolipoprotein E (APOE) binds to TREM2 on TAMs, triggering downstream activation of the DAP12–SYK signaling cascade, which subsequently engages PI3K–AKT and MAPK pathways to initiate a neurogenic transcriptional program." (PMID 41009819, 2025). "To further substantiate the influence of APOE on the modulation of the tumor microenvironment, we conducted in vivo animal experiments." (PMID 40365288, 2025). "Collectively, ICB-resistant tumor exhibits an exhausted CD8+ TEF phenotype and demonstrate a reduced capacity for chemokine secretion, potentially influenced by APOE+ macrophages or tumor cell reprogramming." (PMID 40303328, 2025). "There was a decrease in the infiltration of CD8+ T cells into the subcutaneous tumours of ApoE−/− mice." (PMID 40662483, 2025). "Highly expressed characteristic genes such as C1QA and APOE.The expression of M2 macrophage marker genes in MS4A4A+ TAMs within tumor samples is significantly higher than that in normal tissues, indicating an immunosuppressive role." (PMID 40191203, 2025). "Similar to the results of previous subcutaneous tumour formation, in ApoE−/− mice, we observed a decrease in CD8+ T cell infiltration." (PMID 40662483, 2025). "This situation highlights the critical balance between tumour‐ and host‐derived ApoE in determining its overall impact on cancer development, especially regarding proliferation and metastasis." (PMID 40662483, 2025). "APOE holds the potential to revitalize the tumor microenvironment and augment the efficacy of ICI therapy." (PMID 40365288, 2025). "Through CCIs network analysis, we confirmed extensive communication hubs mediated by Macro_APOE involving tumor cells and other immune cells, such as CD8Tex populations." (PMID 40963562, 2025). "This suggests that patients with lateral cervical LNM exhibit lower APOE expression levels in tumour cells relative to normal cells." (PMID 39810624, 2025). "When examining APOE expression across these 13 tumour subclusters, we observed a striking correlation between lower APOE levels and later‐stage tumour cell states." (PMID 39810624, 2025). "Collectively, these results suggest that APOE-high myeloid cells in metastatic LNs highly express the genes supporting tumor growth, angiogenesis, and immune evasion." (PMID 40835684, 2025). "Intriguingly, we observed a higher level of APOE expression within the core of the tumour compared to the tumour edge." (PMID 39810624, 2025).
tumor (continued). "This investigation provides valuable insights into the role of ApoE in modulating the immune‐tumour interaction within the intracranial microenvironment." (PMID 40662483, 2025). "A unique cluster of tumor cells in D‐TGCT is identified that regulated differentiation of CD34+ fibroblasts into MMP3+ fibroblasts or APOE+ fibroblasts via COL6A3 − (ITGAV + ITGB8) interaction." (PMID 40126353, 2025). "This newfound understanding is reshaping perspectives on APOE, not only as a regulator of metabolic processes but also as a key player in tumor immunology." (PMID 39990672, 2025). "In a 4T1 tumor‐bearing mice model, the APOE inhibitor combined with ICI treatment shows the best efficacy." (PMID 38569519, 2024). "In recent years, APOE has frequently appeared in tumor research and has gradually become recognized as a tumor biomarker." (PMID 39194522, 2024). "In order to confirm the presence of CD14+APOE+ cells and MMP7 tumour cells in close proximity, we determined the association between MMP7 and CD14 as well as APOE in a substantial group of NSCLC patients." (PMID 39187937, 2024). "Cancer in ApoE knockout (ApoE−/−) mice has a lower tumor burden, less fibrosis, reduced innate immune response, and increased adaptive immune cell infiltration while inhibiting ApoE potentiates immune checkpoint inhibitors (ICIs) effectiveness for cancer." (PMID 39695088, 2024). "LILRB4 is a well-known marker of monocytic leukemia, and it supports tumor cell infiltration into tissues and inhibits the proliferation and activation of T lymphocytes through a signaling pathway involving APOE–LILRB4–SHP2–uPAR–ARG1 in AML cells." (PMID 38397424, 2024). "Both CD14+APOE+ cells and MMP7+ tumour cells were associated with poorer survival outcomes and unfavourable immunotherapy response, underscoring their potential as biomarkers in NSCLC." (PMID 39187937, 2024). "Within immune exclusion samples, APOE was discovered to have a significant level of expression in intra‐tumour immune infiltration." (PMID 39187937, 2024). "The expression of MMP7 in tumour cells and APOE in myeloid cells was higher in non‐responder (NR) patients compared to responders (R)." (PMID 39187937, 2024). "ApoE exosomes derived from tumor-infiltrating M2 macrophages can activate PI3K-AKT signaling and promote cytoskeletal remodeling, increasing GC cell migration potential." (PMID 39251966, 2024). "We further aimed to identify tumour‐specific genes that induce CD14+APOE+ cells infiltration and exert immunosuppressive effects on the tumour TME." (PMID 39187937, 2024). "Our results reveal a subset of tumor cells expressing high levels of ApoE, with ApoE-positive endothelial cells (ECs) and ApoE-positive neutrophils positioned close to each other." (PMID 39695088, 2024). "Genes such as APOE, TREM2, VENTX, and C1QA are associated with tumor growth and progression, promotion of apoptosis, and inflammation." (PMID 38910324, 2024). "APOE exhibited substantial expression in the tumour region of immune exclusion samples, while it displayed low levels of expression in immune activation samples." (PMID 39187937, 2024). "ApoE inhibits tumor cell immunogenicity by directly binding to and inhibiting BiP function to reduce tumor MHC-I expression, thereby conferring resistance to immunotherapy." (PMID 39896803, 2024). "Short term survival samples are enriched for SMA,VIM, and PDGFR CAFs, and show more crosstalk between CAF APOE and tumor LRP5 at the tumor-stroma interface, supported by staining and in vitro experiments." (PMID 38525245, 2024). "Second, while our spatial analysis revealed the co‐location of CD14+APOE+ cells with MMP7+ tumour cells, the functional implications of this co‐localisation were inferred based on known roles of these cell types and their expression profiles." (PMID 39187937, 2024). "In particular, the reduced level of M2 macrophage and tumour progression suppression were observed in PCa xenografts which implanted in Apolipoprotein E‐knockout mice." (PMID 39138838, 2024).